ZNF750 (zinc finger protein 750)
Diseases named in the same sentence as ZNF750 in open-access papers (continued):
Sharing a sentence is not in itself a finding about the gene and the disease.
tumor (continued). "Mechanistically, ZNF750 has been reported to mediate tumor-suppressive roles by regulating the expression of various downstream genes, such as TINCR, LAMC2, DANCR, FGF14, and SNAI1." (PMID 37365152, 2023). "Collectively, all these results suggest a model for how TRIM29 acts as a tumor suppressor via modulating ZNF750 expression in ESCC." (PMID 37365152, 2023). "Specifically, ZNF750 expression decreases with the increase in tumor aggressiveness, with a full impairment in metastatic lesions." (PMID 37047491, 2023). "Mechanistically, TRIM29 functioned as a positive regulator of tumor suppressor gene ZNF750 via modulating IL6/STAT3 signaling pathway." (PMID 37365152, 2023). "In summary, this study explores the oncosuppressive function of TRIM29 in ESCC and reveals that TRIM29 downregulation due to hypermethylation of its promoter, positively regulates tumor suppresser gene ZNF750 via modulating IL6/STAT3 signaling pathway." (PMID 37365152, 2023). "Mechanistically, TRIM29 downregulation suppresses the expression of the tumor suppressor ZNF750 by activating the STAT3 signaling pathway." (PMID 37365152, 2023). "ZNF750, zinc finger protein 750, has been established as a tumour suppressor in oesophageal squamous cell carcinoma though it is absent from the CGC diver gene list." (PMID 34997044, 2022). "Previous work has demonstrated that ZNF750 can suppress the malignant progression of OSCCs by regulating the tumor vascular microenvironment." (PMID 34176441, 2021). "Parallel in other cell type support a potential tumor suppressor role of ZNF750, the present study testified that ZNF750 attenuated cell invasion, migration and MMP13 positive population." (PMID 35003347, 2021). "The detail mechanism of ZNF750 on tumor suppressing in OSCC involved by E2F2 will be further investigated in the future." (PMID 35003347, 2021). "The tumor growth and metastasis was repressed by ZNF750 manifested by reduced tumor size, tumor weight and the genes related to cell proliferation and metastasis." (PMID 35003347, 2021). "TINCR is one of the downstream targets of ZNF750, and it mediates ZNF750 tumour suppression and the expression of important molecules that induce differentiation." (PMID 34187411, 2021). "The expression level of Ki67 and PCNA in oe-ZNF750 and sh-ZNF750 groups was in consistent with the observation results from the tumor growth." (PMID 35003347, 2021). "ZNF750 induces cell cycle arrest in the G0/G1 phase and regulates the tumor vascular microenvironment to inhibit oral squamous cell carcinoma's malignant progression." (PMID 34504527, 2021). "The present study showed that the tumor volumes were smaller in oe-ZNF750 groups than in oe-con groups at check point, but it was bigger in sh-ZNF750 groups than in sh-Con groups." (PMID 35003347, 2021). "This study extends these activities of resveratrol to OSCC cells, and it suggests that the antitumor efficacy against this disease involves activation of ZNF750-dependent tumor-suppressive pathways." (PMID 34176441, 2021). "Other ZNF members including ZNF281, ZNF185 and ZNF750 serve as oncogenes or tumor suppressor genes in different cancers." (PMID 34670480, 2021). "The elevated expression level of Ki67 and PCNA in oe-ZNF750 and diminished level in sh-ZNF750 groups was in consistent with the observation results from the tumor growth in vivo." (PMID 35003347, 2021). "Our observation that resveratrol also upregulates ZNF750 suggests that this endogenous tumor suppressor mediates at least some of the changes in the tumor microenvironment." (PMID 34176441, 2021). "We further immunohistochemically stained the tumor tissue samples with anti-ZNF750 and anti-Ki-67 antibody and found that Ki-67 staining intensity in ZNF750 overexpressed group (ZNF750wt) was significantly weaker than that of the control group (KYSE150NC)." (PMID 32042337, 2020). "Overall, our findings provide a novel molecular mechanism by which ZNF750 acts as tumour suppressor gene." (PMID 33298895, 2020).
tumor (continued). "Meanwhile, ZNF750 inhibited the malignant progression of oral squamous cell carcinoma by regulating tumor vascular microenvironment." (PMID 32341351, 2020). "The results showed the nucleus/cytoplasm ratio of ZNF750 in ESCC was significantly lower than that in paired non-tumor tissues (P < 0.001)." (PMID 32042337, 2020). "The pattern and significance of ZNF750 genetic alterations and expression promote us to investigate the correlation of ZNF750 with tumor metastasis in ESCC." (PMID 32341351, 2020). "Together, our results suggest that ZNF750 plays a tumor suppressive role via DANCR/miR-4707-3p/FOXC2 axis that works in a ceRNA manner in ESCC." (PMID 32341351, 2020). "Chromatin immunoprecipitation sequencing identified that ZNF750 directly regulated FGF14 (encoding fibroblast growth factor 14), ablation of which reversed ZNF750’s tumor repressor effect." (PMID 30518868, 2018). "The tumor suppressing activity of ZNF750 with significant prognostic power in multiple squamous cell carcinomas is confirmed by independent reports." (PMID 30012096, 2018). "Overexpression of ZNF750 blocked tumor cell growth in vitro and in vivo, while FGF14 functions as the downstream target of ZNF750 to regulate NPC apoptosis." (PMID 30518868, 2018). "These mutations are located in the C2H2 zinc-finger domain, suggesting the importance of the zinc-finger domain in mediating the tumour suppressor activity of ZNF750." (PMID 29152378, 2017). "In this study, we identified TNC as a downstream regulator of tumor suppressor ZNF750." (PMID 38711034, 2024). "Notably, ZNF750 has been validated as a lineage-specific tumor suppressor in squamous cell carcinoma." (PMID 38711034, 2024). "Furthermore, overexpression of ZNF750 in H226 cells markedly decelerated tumor growth in mice bearing H226 subcutaneous xenograft tumors (P = 0.003, scale bar = 1 cm)." (PMID 38711034, 2024). "Moreover, ZNF750 functions as a tumor suppressor through inhibiting the proliferation, invasion, and metastasis of ESCC." (PMID 37365152, 2023). "Furthermore, the tumor weight was reduced in oe-ZNF750 groups but it was increased in sh-ZNF750 groups than in their matched control groups, which indicated that ZNF750 had significant inhibitory effect on tumor growth." (PMID 35003347, 2021). "ZNF750 may suppress malignant progression of OSCC by regulating the tumor vascular microenvironment." (PMID 34176441, 2021). "Moreover, the proliferation markers Ki67 and PCNA protein expression in xenograft tumor samples was lower in the oe-ZNF750 groups than in oe-Con groups, whereas, it was higher expressed in sh-ZNF750 groups than in sh-Con groups." (PMID 35003347, 2021). "In line with above studies, we proofed that the changes of ZNF750 expression led to the changes of tumor growth, which manifested by decreased tumor volume and tumor weight, reduced Ki67 and PCNA expression in oe-ZNF750 groups, but all of these was increased in sh-ZNF750 groups." (PMID 35003347, 2021). "Given the ability of the natural phytoalexin resveratrol to reduce the risk of OSCC as well as other cancers, we wondered whether this compound may interact with the endogenous tumor-suppressing activity of ZNF750/RAC1 signaling pathway in OSCC cells." (PMID 34176441, 2021). "Previous study has demonstrated that ZNF750 could suppress the malignant progression of OSCCs by regulating tumor vascular microenvironment." (PMID 34176441, 2021). "Clinically, we observed a significant correlation of patient ZNF750 genotype with tumor phenotype." (PMID 32341351, 2020). "We have previously demonstrated that ZNF750 acts as a tumour suppressor in breast cancer." (PMID 33298895, 2020). "We found ZNF750 was decreased in ESCC tumors compared to that of paired non-tumor tissues and the ratio of ZNF750 protein in nucleus and cytoplasm may be a promising prognostic biomarker for ESCC patients." (PMID 32042337, 2020).
tumor (continued). "Recent attempts to decipher the significance of ZNF750 for tumorigenesis in ESCC have revealed that ZNF750 might act as a tumor suppressor gene." (PMID 32341351, 2020). "Together with our observations in vitro and in vivo, our findings suggest that ZNF750, a significantly mutated driver gene in ESCC, may regulate tumor angiogenesis via DANCR/miR-4707-3p/FOXC2 axis that works in a ceRNA manner." (PMID 32341351, 2020). "In conclusion, our work shows that ZNF750, a novel significantly mutated gene in ESCC, may act as a tumor suppressor via directly regulating SNAI1 expression and inhibit the EMT process of ESCC cells." (PMID 32042337, 2020). "The genetic data indicated that ZNF750 might act as a tumor suppressor gene in ESCC based on the rule of 20/2019." (PMID 32042337, 2020). "In addition, ZNF750 has been described as a tumour suppressor protein in squamous cell carcinomas (SCCs) of the oesophagus and lung." (PMID 33298895, 2020). "Additionally, across 97 pairs of RNA-seq dataset, ZNF750 expression level was significantly decreased in tumor samples in comparison with matched normal samples." (PMID 32341351, 2020). "The genetic data and the IHC analysis of ESCC samples indicated that ZNF750 might act as a tumor suppressor gene in ESCC." (PMID 32042337, 2020). "We then explored the functional relevance of ZNF750 with tumor angiogenesis in ESCC." (PMID 32341351, 2020). "Collectively, these results indicate that ZNF750 may be a critical suppressor of tumor angiogenesis to regulate metastasis of ESCC." (PMID 32341351, 2020). "To further confirm the tumor suppressor role of ZNF750 in ESCC, we establish a subcutaneous transplantation tumor model in BALB/c-nu mice using KYSE150 cells with wild-type ZNF750 stable overexpression (KYSE150-ZNF750wt) and the negative control cells (KYSE150-NC)." (PMID 32042337, 2020). "We found that ectopic expression of ZNF750 blocked tumor cell growth." (PMID 30518868, 2018). "Moreover, the inhibition of NPC tumor growth in mice after ZNF750 overexpression was reversed by FGF14 knockdown." (PMID 30518868, 2018). "In line with above studies, ZNF750 up-regulated the EMP1 may reduce the tumor cell invasion and metastasis." (PMID 29416636, 2018). "We then asked whether inhibiting FGF14 would reverse the tumor repressor function of ZNF750 in vitro and in vivo." (PMID 30518868, 2018). "In contrast, ZNF750 as a tumor suppressor inhibits OSCC cell invasion and migration, suggesting that ZNF750 may inhibit cell metastasis during OSCC progression." (PMID 30483394, 2018). "Our studies revealed that ZNF750 is reduced or deleted in all detected OSCC tumor tissues." (PMID 29416636, 2018). "It will be very helpful to elucidate the inhibited role of ZNF750 in OSCC tumor development." (PMID 29416636, 2018). "Interestingly, overexpression of the C2H2 ZNF750 mutant is not able to suppress tumour growth, demonstrating that the C2H2 zinc-finger domain is essential for the tumour suppressor activity of ZNF750." (PMID 29152378, 2017). "Therefore, we postulated that ZNF750 may be a crucial mediator on Ezh2, leading to reduced tumor growth, metastasis, and the E2F2 was involved in its regulation." (PMID 35003347, 2021). "Importantly, a previous research confirms that ZNF750 exerts a tumor-suppressive effect in CRC." (PMID 34288812, 2021). "The genetic data indicated that ZNF750 might act as a tumor suppressor gene in ESCC." (PMID 32042337, 2020). "Our findings demonstrate that ZNF750 and TNC modulate tumor proliferation, invasion, metastasis, and immunogenicity." (PMID 38711034, 2024).
tumor (continued). "Receiver operating characteristic (ROC) curves demonstrated that both ZNF750 and TNC served as effective markers for distinguishing between tumor and paracancerous tissue." (PMID 38711034, 2024). "ZNF750 regulates TNC expression and affects the proliferation, invasion, migration and immunogenicity of cells in vitro, as well as tumor growth in vivo." (PMID 38711034, 2024). "The correlations of ZNF750 with SNAI1, VIM, CDH2 and CDH1 were verified with our RNA sequencing data of 155 paired of ESCC and matched non-tumor tissues." (PMID 32042337, 2020). "Thus, as a key differentiation inducer of epidermal cells, ZNF750 may be a tumor suppressor in SCC." (PMID 32042337, 2020). "We furtherly analyzed the protein level of ZNF750 in ESCC samples using tissue microarray (TMA), which included 308 ESCC and paired adjacent non‐tumor tissues." (PMID 32042337, 2020). "Thus, FOXC2 may act as a mediator of tumor angiogenesis induced by ZNF750 knockdown in ESCC." (PMID 32341351, 2020). "In this study, we identified that ZNF750, as a hypomethylated gene, was downregulated in NPC tumor tissues and cell lines." (PMID 30518868, 2018). "In the present study, we investigated the ZNF750 protein expression changes in OSCC tumor tissues, and explored the differential gene expression of ten signal transduction pathways involved in CAL-27 cell that over-expression ZNF750 gene." (PMID 29416636, 2018). "Particularly, ZNF750 directly induces the expression of the long non-coding RNA TINCR, through which it regulates cancer cell proliferation and tumour growth and represses the expression of LAMC2, a component of Laminin-332." (PMID 29152378, 2017). "For instance, CIZ1, ZNF217, ZNF281, ZKSCAN3, ZNF692, ZNF750, and ZFP36 proteins are closely related to the tumor volume, lymph node metastasis status, and TNM stage, and their expression levels had statistically significant effects on the survival time of patients with colon adenocarcinoma." (PMID 36358661, 2022). "ZNF750 and ZNF545 have been identified as tumor suppressors." (PMID 34504527, 2021). "Zinc finger protein 750 (ZNF750) and enhancer of zeste homolog 2 (EZH2), which were identified as the tumor suppressor in NPC, could inhibit the growth and metastasis of NPC cells." (PMID 33879256, 2021). "To confirm the inhibitory effect of ZNF750 on tumor growth in vivo, we subcutaneously injected the stable cell lines CAL-27oeCon, CAL-27oeZNF750, CAL-27shCon and CAL-27shZNF750 into nude mice, and then the tumor volume was measured about weekly for 40 days." (PMID 35003347, 2021). "The ZNF750 mRNA expression was significantly increased 4505.9-folds and 55.8-folds in the CAL-27oeZNF750 cells and xenograft tumor samples respectively, while knockdown of the ZNF750 gene leaded to 77.8% and 60% down-regulation of ZNF750 in the CAL-27shZNF750 cells and xenografts tumor samples." (PMID 35003347, 2021). "Collectively, the ability of resveratrol to suppress the progression of OSCC may involve activation of the ZNF750/RAC1 signaling pathway and modification of the tumor vascular microenvironment." (PMID 34176441, 2021). "Our findings identified FGF14 as the direct target gene of ZNF750, and the ZNF750-FGF14 signaling axis inhibited NPC growth through promoting cell apoptosis, which broadened our understanding of ZNF750 in repressing tumor development." (PMID 30518868, 2018). "Moreover, chromatin immunoprecipitation sequencing (ChIP-Seq) identified fibroblast growth factor 14 (FGF14) as the downstream target of ZNF750, and blocking FGF14 reversed the tumor repressor effect of ZNF750 in NPC cells." (PMID 30518868, 2018). "Furthermore, it is most likely that TRIM29 could regulate expression of ZNF750 and KRT5 in other tumors, as TRIM29 expression positively correlated with the expression of ZNF750 and KRT5 significantly in 18 tumor types, such as BLCA, CESC, HNSC, LUSC, PRAD, and SKCM." (PMID 37365152, 2023).
tumor (continued). "Given that the DANCR/miR-4707-3p/FOXC2 axis in ESCC, we hypothesize ZNF750 may directly downregulate DANCR expression, strengthened the interaction of miR-4707-3p with FOXC2-3′UTR in a ceRNA manner, leading to degradation of FOXC2 mRNA, thus playing tumor suppressive role in ESCC." (PMID 32341351, 2020). "We also found a ZNF750 in-frame insertion in early-passage HCI-001 PDXs but not in later-passage PDXs nor in early- or late-passage PDxOs and a frameshift deletion of MYH9 that was observed in HCI-019 PDxOs but not in the PDXs or human tumor." (PMID 35221336, 2022).